NR4A1 (nuclear receptor subfamily 4 group A member 1)
Diseases named in the same sentence as NR4A1 in open-access papers (continued):
Sharing a sentence is not in itself a finding about the gene and the disease.
Hyperinsulinemia (6 papers, 2013 to 2025). An increased concentration of insulin in the blood. "Moreover, we have shown that there is a significant dysregulation of the Akt-Nr4a1 pathway within the endometrium of PCOS rats, offering fresh insights into the underlying mechanisms of infertility linked to hyperinsulinism in PCOS." (PMID 38310251, 2024).
Infertility (6 papers, 2010 to 2024). "In addition, it is thought that altered expression of NR4A1 in reproductive-age women with EMS may be associated with infertility." (PMID 39408909, 2024).
papillary carcinoma (6 papers, 2005 to 2024). A malignant epithelial neoplasm characterized by a papillary growth pattern. "Both NR4A1 and TREM2 are regulated by thyroid hormones and promote papillary thyroid cancer progression." (PMID 39719972, 2024).
psoriasis (6 papers, 2016 to 2025). An autoimmune condition characterized by red, well-delineated plaques with silvery scales that are usually on the extensor surfaces and scalp. "Over-representation of Tregs, dysfunctional NR4A1-expressing T cells, and senescent SESN3+ T cells were detected in psoriasis." (PMID 34777377, 2021). "Psoriasis skin-derived S.B cells expressed GPX4, FTL, and FTH1 at high levels, whereas control skin-derived S.G & S.S cells expressed high levels of GPX4, FTH1, NR4A1, NFE2L2, and MT1G." (PMID 35962439, 2022). "We further found that a sub-cluster of T cells, which express NR4A1, a transcription factor indicative of dysfunctional T cells, and are enriched for genes involved in nuclear organization (NEAT and ANKRD36), was over-represented in psoriasis samples." (PMID 33053333, 2020). "Additional shared signatures between ILCs and T cells were related to genes that regulate tissue residency (FOS and NR4A1; module 18) as well as quiescence (TSC22D3, DUSP1, ZFP36L2, and KLF6; module 22), the latter recently shown to be expressed by plastic skin ILCs in a mouse model of psoriasis." (PMID 37160121, 2023).
Anxiety (5 papers, 2011 to 2025). Intense feelings of nervousness, tension, or panic often arise in response to interpersonal stresses. "In addition, variable expression between animals in the striatal-like regions of the amygdala indicates that the Nr4a1-eGFP strain might be useful for identification of circuits involved in anxiety-like behavior." (PMID 21305052, 2011).
ischemic stroke (5 papers, 2021 to 2023). A stroke disorder caused by obstruction of blood flow to the brain, due to thrombotic (local blood clot formation) or embolic (due to a blood clot or other material traveling from another site) event. "Consistent with the in vitro results, NR4A1 levels are increased in microglia after ischemic stroke in both rodents and humans." (PMID 37490433, 2023). "Using NR4A1 global knockout mice, Liu and colleagues further demonstrate that loss of NR4A1 leads to increased TNF expression and worse outcomes in a mouse model of ischemic stroke." (PMID 37490433, 2023). "Taken together, these data suggest that Nr4a1-knockout significantly promoted Tnf expression and exacerbated brain injury in experimental ischemic stroke." (PMID 37486903, 2023). "Remarkably, conditional microglial deletion of Nr4a1 elevates Tnf expression and worsens outcomes in a mouse model of ischemic stroke, in which case NR4A1 expression is significantly induced in the cytoplasm of microglia." (PMID 37486903, 2023). "Similar to the NR4A1 global knockout mice, loss of NR4A1 in microglia specifically results in increased TNF expression and aggravated outcomes after ischemic stroke." (PMID 37490433, 2023). "NR4A1 inhibits inflammatory responses and reduces the infarct volume in ischemic stroke." (PMID 37452512, 2023). "Since a large number of peripheral immune cells could infiltrate the brain after ischemic stroke, it would be difficult to differ the function of microglial NR4A1 and NR4A1 in other immune cells in Nr4a1-knockout mice." (PMID 37486903, 2023). "However, in Tmem119-CreERT2; Nr4a1fl/fl mice, microglial NR4A1 was specifically knockout, enabling us to confirm the neuroprotective role of microglial NR4A1 in the context of ischemic stroke." (PMID 37486903, 2023). "Besides, it is thought that NR4A1 plays an important role in the regulation of neuroinflammation and in neural apoptosis after ischemic stroke." (PMID 36707762, 2023). "Thus, we found that microglial NR4A1 was significantly up-regulated in the cytoplasm at the acute phase after ischemic stroke, suggesting cytoplasmic NR4A1 might play an important role in the pathophysiology of ischemic stroke." (PMID 37486903, 2023). "Furthermore, to mimic microglial activation in ischemic stroke in vitro, we induced neuronal injury by incubating neurons in oxygen-glucose deprivation (OGD) conditions and then treated WT and Nr4a1-/- primary microglia with neuron-conditioned media (NCM) from control or OGD-exposed neurons." (PMID 37486903, 2023).
Myocardial fibrosis (5 papers, 2021 to 2024). "Another study showed that blockade of the translocation of Nr4a1 to the cytoplasm contributed to bellidifolin-mediated anti-fibrotic effect on isoprenaline-induced myocardial fibrosis." (PMID 37161357, 2023). "Our results verified that BEL prevented myocardial fibrosis by inhibiting NR4A1 phosphorylation and impeding NR4A1 nucleus to cytoplasmic transformation in CFs." (PMID 33995055, 2021). "The inhibitory mechanism of BEL on myocardial fibrosis was verified by regulating the TGF-β/Smads and p38 pathway and preventing NR4A1 cytoplasmic localization." (PMID 33995055, 2021).
myocardial ischemia (5 papers, 2014 to 2025). A disorder of cardiac function caused by insufficient blood flow to the muscle tissue of the heart. "In the heart, Nr4a1 expression is induced by stimuli that cause adverse cardiac remodeling, and under conditions of myocardial ischemia Nr4a1 is again protective since its deletion in mice caused a malformed infarct scar, and consequently, reduced cardiac function." (PMID 39644367, 2024). "However, the importance of Nr4a1 to macrophage phenotype has only been studied in detail in myocardial ischemia, where Nr4a1 deficiency impaired the resolution of inflammation leading to defective scar formation." (PMID 39644367, 2024). "A second member of the Nr4a family of stress response genes, Nr4a1, is also strongly upregulated by cardiac ischemia and α1aAR stimulation." (PMID 26244980, 2015). "The first identification of NR4A1 (Nur77) in the regulation of cardiomyocyte death comes from a mouse model subjected to 50 min of cardiac ischemia followed by 50 min and 120 min reperfusion." (PMID 24733352, 2014). "Hence Nr4a1 deletion reduces ECM production in both myocardial ischemia and Ang II models, however, while this is advantageous in a non-ischemic setting (i.e. Ang II), it is detrimental in ischemia where proper scar formation is essential to long-term cardiac function." (PMID 39644367, 2024). "Whilst the reduction in fibrosis brought about by the absence of Nr4a1 proved to be advantageous in the non-ischemic model used in our study, this is an interesting contrast to myocardial ischemia." (PMID 39644367, 2024).
renal cell carcinoma (5 papers, 2015 to 2024). "HIF-1α binds to the putative HIF-responsive element present in the Nr4a1 promoter, thereby including NR4A1 expression in renal cell carcinoma." (PMID 38539632, 2024). "Transfection of renal cell carcinoma (RCC) ACHN and 786-O cells with oligonucleotides that target NR4A1 results in a 40–60% decrease in cell proliferation and induction of apoptosis." (PMID 26035713, 2015).
ulcerative colitis (5 papers, 2015 to 2025). An inflammatory bowel disease involving the mucosal surface of the large intestine and rectum. "Similar protective effects of NR4A1 were observed in another study, and it was also reported that NR4A1 SNPs with lower activity than wild-type NR4A1 were associated with increased risks for ulcerative colitis and Crohn’s disease." (PMID 40871737, 2025). "For example, both NR4A1 and ANXA5 were associated with ulcerative colitis (UC); NR4A1 expressed in intestine tissues, inflammatory cells and epithelium, regulated the differentiation and function of Paneth cell; ANXA5 had differential expression in the jejunal mucosa of IUGR and normal piglets." (PMID 41190166, 2025). "We next examined NR4A1 and NLRP3 activation in intestinal tissue sections from patients with ulcerative colitis and found increased activation of these proteins in CD68+ macrophages in active UC compared to remission." (PMID 40596758, 2025).
Ureteral obstruction (5 papers, 2022 to 2025). Obstruction of the flow of urine through the ureter. "Inhibition of the P13K/AKT pathway and VEGF was associated with NR4A1-mediated inhibition of basal and unilateral ureteral obstruction-induced effects in mouse models." (PMID 40871737, 2025). "In addition, most of these same parameters were also increased in NR4A1-deficient mice, demonstrating the protective role of NR4A1 against unilateral ureteral obstruction (UUO)-induced fibrosis." (PMID 40871737, 2025). "Unilateral ureteral obstruction (UUO) in mice induced NR4A1 and enhanced fibrosis and interstitial kidney damage and CsnB enhanced this response, and similar enhancement was observed in a TGFβ-induced response in vitro." (PMID 40871737, 2025). "On the one hand, the activation of Nr4a1 alleviated renal interstitial fibrosis resulting from ureteral obstruction." (PMID 41332397, 2025).
chronic kidney disease (4 papers, 2021 to 2026). Impairment of the renal function secondary to chronic kidney damage persisting for three or more months. "In chronic kidney disease, the deficiency of NR4A1 has been proved to be involved in the process of renal injury and renal dysfunction." (PMID 35186975, 2021). "Nuclear receptor 4A1 (NR4A1) is a gene that increases the likelihood of chronic kidney disease (CKD) and contributes to its development." (PMID 39736520, 2024).
endothelial dysfunction (4 papers, 2022 to 2025). In vascular diseases, endothelial dysfunction is a systemic pathological state of the endothelium (the inner lining of blood vessels) and can be broadly defined as an imbalance between vasodilating and vasoconstricting substances produced by (or acting on) the endothelium. "Here, we demonstrate a marked elevation in Nr4a1 expression following myocardial IR injury, which is associated with impaired cardiac function, heightened cardiomyocyte apoptosis, exacerbated inflammatory responses, and endothelial dysfunction." (PMID 39744420, 2025). "Nr4a1 promotes high fat-related endothelial dysfunction by promoting the CaMKII–Parkin–mitochondrial autophagy pathway." (PMID 35812340, 2022).
kidney cancer (4 papers, 2015 to 2025). Primary or metastatic malignant neoplasm involving the kidney. "Currently, we are accumulating tumors from kidney cancer patients to investigate the tumor-type specific expression and prognostic significance of NR4A1." (PMID 26035713, 2015).
kidney damage (4 papers, 2022 to 2025). "To identify whether Nur77 deficiency–mediated Sirt1 degradation was the key process in aging nephropathy, we treated aged WT and Nr4a1−/−mice with the activator, resveratrol (Res)." (PMID 36883265, 2023). "Knocking down NR4A1 could exacerbate infiltration of inflammatory cells and more severe kidney damage (P < 0.05)." (PMID 39736520, 2024).
lung fibrosis (4 papers, 2022 to 2024). "NR4A1 phosphorylation decreases the transcriptional activity of NR4A1, and pNR4A1 is strongly associated with hepatic/lung fibrosis and is mainly located in the cytoplasm, whereas pan-NR4A1 localizes in both nuclear and cytoplasmic compartments." (PMID 35600274, 2022). "The Net-M5 detected genes involved in lung fibrosis (CXCL8 and IL1B), VEGFA-VEGFR2 signaling (NR4A1 and CBL), and TGF-β signaling (JUNB and ATF3)." (PMID 38259488, 2023).
lupus (4 papers, 2022 to 2025). "Minocycline-mediated deactivation of microglia, antibody blockade of C1q, or neuronal restoration of Nr4a1 protected lupus mice from synapse loss and NP manifestations." (PMID 35177587, 2022). "Indeed, most Nr4a1-controlling genes (Grin1, Creb3l3, Mef2a, Mef2c, and Mef2d) were reduced in the lupus hippocampus, as revealed by sequencing assays." (PMID 35177587, 2022). "Based on these findings, by mining sequencing data, we found a specific reduction in a set of activity-dependent genes regulating the actin cytoskeleton in the lupus hippocampus, which constitute the NMDAR/NR4A1/CREB transcriptional mechanisms." (PMID 35177587, 2022).
medulloblastoma (4 papers, 2016 to 2023). A malignant, invasive embryonal neoplasm arising from the cerebellum. "Nr4a1 overexpression increased medulloblastoma cell growth and viability, while Nr4a1 knock down decreased proliferation." (PMID 31683815, 2019).
osteosarcoma (4 papers, 2017 to 2024). A usually aggressive malignant bone-forming mesenchymal neoplasm, predominantly affecting adolescents and young adults. "Genes such as EGFL7 and VEGF were differentially expressed in osteosarcoma, and NR4A1 was found to play a key role in osteosarcoma pathophysiology." (PMID 39324133, 2024). "The expression of NR4A1 was significantly higher in osteosarcoma tissues from patients with poor chemosensitivity than that from patients with good chemosensitivity." (PMID 35965537, 2022). "The expression of NR4A1 was significantly higher in osteosarcoma tissues from patients with poor chemosensitivity than that from patients with good chemosensitivity as validated from GSE154540." (PMID 35965537, 2022). "The expression of NR4A1 was significantly higher in the metastasis osteosarcoma tissues than that in the primary osteosarcoma tissues as validated from GSE32981 and GSE154540." (PMID 35965537, 2022). "Thirdly, the study was mainly based on the bioinformatics analysis, and further validation studies should be performed to further explore the role of NR4A1 in osteosarcoma progression." (PMID 35965537, 2022). "The percentage of osteoblasts with a high NR4A1 expression and low NR4A1 expression in the primary, metastasis, and recurrent osteosarcoma tissues was further analyzed in GSE152048." (PMID 35965537, 2022). "A high expression of NR4A1 in the osteosarcoma tissues was significantly correlated with shorter 5-year overall survival of patients with osteosarcoma." (PMID 35965537, 2022). "A high expression of NR4A1 in the osteosarcoma tissues was significantly correlated with a shorter 5-year overall survival of patients with osteosarcoma." (PMID 35965537, 2022). "In order to further validate the expression of NR4A1 in the osteosarcoma tissues, we further explored two datasets, namely, GSE32981 and GSE154540." (PMID 35965537, 2022). "The expression of NR4A1 was significantly higher in the metastasis osteosarcoma tissues than in the primary osteosarcoma tissues as validated from GSE32981 and GSE154540." (PMID 35965537, 2022). "The percentage of osteoblasts with a high NR4A1 expression was higher in the recurrent osteosarcoma tissues than that with a low NR4A1 expression." (PMID 35965537, 2022). "The expression of NR4A1 was significantly higher in the metastasis osteosarcoma tissues than that in the primary osteosarcoma tissues." (PMID 35965537, 2022). "Further analysis of the scRNA-seq data revealed that the percentage of osteoblasts with a high NR4A1 expression was higher in the recurrent osteosarcoma tissues than that with a low NR4A1 expression." (PMID 35965537, 2022). "In conclusion, the present study may suggest that NR4A1 may be an important prognostic biomarker for osteosarcoma progression." (PMID 35965537, 2022). "Our results may indicate that NR4A1 may play an important role in the TME of osteosarcoma and may contribute to the metastasis and recurrent of osteosarcoma." (PMID 35965537, 2022). "In addition, we also examined if NR4A1 was differentially expressed in the osteosarcoma tissues from patients with different chemo-sensitivities." (PMID 35965537, 2022). "In “Pericyte”, differentially expressed NRs such as NR4A1, NR3C1, NR2F2, NR2F1, NR1H2, and ROR were detected among metastasis, primary, and recurrent osteosarcoma tissues." (PMID 35965537, 2022). "Based on our analysis, we found that several NRs including NR4A2, NR4A1, NR3C1, NR2F6, and NR2F2 were differentially expressed in osteoblastic cells among metastasis, primary, and recurrent osteosarcomas." (PMID 35965537, 2022). "In “Myeloid”, differentially expressed NRs such as NR4A2, NR4A1, NR3C1, RXRA, NR1D2, PPARD, and RARA were identified among metastasis, primary, and recurrent osteosarcoma tissues." (PMID 35965537, 2022). "Furthermore, several NRs such as NR4A2, NR4A1, and NR3C1 have been found to be differentially expressed in most types of DEGs among metastasis, primary, and recurrent osteosarcomas." (PMID 35965537, 2022).
osteosarcoma (continued). "Furthermore, several NRs such as NR4A2, NR4A1, and NR3C1 have been found to be differentially expressed in most types of DEGs among metastasis, primary, and recurrent osteosarcoma." (PMID 35965537, 2022). "Similarly, the role of NR4A1 has been well studied in other types of cancers but not in osteosarcoma." (PMID 35965537, 2022).
pulmonary arterial hypertension (4 papers, 2020 to 2025). Pulmonary arterial hypertension (PAH) is a group of diseases characterized by mean pulmonary artery pressure >20 mmHg and elevated pulmonary arterial resistance leading to right heart failure. "Studies in mice with hypoxia-induced pulmonary hypertension also demonstrate a protective role for NR4A1." (PMID 40871737, 2025). "Pulmonary arterial hypertension (PAH) is a serious disease in humans and NR4A1 is downregulated in PASMCs in humans with PAH, and overexpression of NR4A1 in PASMCs blocked cell proliferation and migration." (PMID 40871737, 2025). "In patients with pulmonary arterial hypertension (PAH), the pulmonary artery smooth muscle cells (PASMCs) exhibited increased proliferation and survival and decreased expression of NR4A1, NR4A2, and NR4A3 (protein and mRNA) compared to normal lung PASMCs." (PMID 40871737, 2025).
alopecia (3 papers, 2021 to 2023). Hair loss usually from the scalp. "The pathologic phenotypes of 15‐month‐old Nr4a1−/− mice showed more obvious alopecia, intervertebral disk degeneration, and greater abdominal circumferences than WT mice of the same age, which may be due to the role of Nur77 in lipid‐lowering." (PMID 36883265, 2023).
autism (3 papers, 2016 to 2023). Persistent deficits in social interaction and communication and interaction as well as a markedly restricted repertoire of activity and interest as well as repetitive patterns of behavior. "Drug-induced activation of NR4A1 to compensate for its low expression in a model of autism reduced the number of surplus synapses offering perspectives for therapeutic intervention." (PMID 29295823, 2018).
B cell lymphoma (3 papers, 2021 to 2025). "In contrast, the overexpression of NR4A1 in B cell lymphomas was associated with reduced tumor growth and increased rates of tumor cell apoptosis, while the low expression of NR4A1 led to increased tumor growth and poor clinical outcomes." (PMID 40508074, 2025).
COVID-19 (3 papers, 2021 to 2023). A disease caused by infection with severe acute respiratory syndrome coronavirus 2. "In addition, the combination of SAMD9, GZMB, JUNB, and NR4A1 presented excellent diagnostic value in COVID-19." (PMID 38384322, 2023). "In the present study, we identified six shared genes (SAMD9, PLEK, GZMB, JUNB, NR4A1, and NR1D1) of MG and COVID-19 patients through bioinformatic analysis." (PMID 38384322, 2023). "The differential expression analysis identified six differentially expressed genes (DEGs) shared by myasthenia gravis (MG) and COVID-19, namely SAMD9, PLEK, GZMB, JUNB, NR4A1, and NR1D1." (PMID 38384322, 2023).